GZMB (granzyme B)
Diseases named in the same sentence as GZMB in open-access papers (continued):
Sharing a sentence is not in itself a finding about the gene and the disease.
tumor (continued). "Peripheral NK cells from obese patients displayed elevated activation markers such as CD69 and granzyme B but defective degranulation and reduced tumor-killing capacity." (PMID 41516046, 2025). "The results showed that both methods were comparable in terms of anti-tumor efficacy, with the group receiving the local low dose showing higher levels of granzyme B (p < 0.05), suggesting better activation of cytotoxic T cells." (PMID 40766321, 2025). "Our data demonstrate that PRF1 and GZMB expression levels are elevated in the peritumoral region compared to the tumor core, suggesting a spatial heterogeneity in cytotoxic immune activity." (PMID 40895524, 2025). "our findings reveal a distinct immune profile with increased CD3+, CD4+, CD8+ and CD20+ lymphocytes in normal tissues adjacent to tumors and a notable presence of granzyme B+ cells in the tumor interface, particularly in patients with structural disease." (PMID 40469283, 2025). "Historically, GZMB expression levels have served as a marker of immune activity, indicative of the potency of anti-tumor immunity." (PMID 41567188, 2025). "They produced less IFN-γ, had lower expression levels of granzyme B and perforin, and were less cytotoxic to tumor target cells." (PMID 40725440, 2025). "CD8+ T cells are key effector cells in the immune system, which directly kill tumor cells by expressing cytotoxic molecules such as Perforin and Granzyme B (GZMB)." (PMID 41573646, 2025). "NK cells exert their anti-tumor effects primarily by secreting perforin, granzyme B, and cytokines such as IFN-γ and TNF-α." (PMID 41280896, 2025). "The specific cytotoxicity of T cells is often indicated by their release of perforin and granzyme B when targeting tumor cells." (PMID 40510363, 2025). "In contrast, there was a decreased density of activated CD4 T cells (CD45RA+GITR+TOX-) and CD8 T cells (CD45RA+GzmB+TOX-) in proximity to tumor cells." (PMID 39803458, 2025). "In vivo experiments showed that HDACi can increase granzyme B in tumors, diminish tumor growth, and promote CD8+ lymphocyte and CD11b+ cell infiltration." (PMID 41291696, 2025). "Effector lymphocytes mobilized by G-CSF + ISO, particularly effector-memory CD8 + T-cells and NK-cells, exhibited upregulated genes and enriched gene sets linked to anti-tumor activity (e.g. NKG7, GZMB, NK cells cytotoxicity)." (PMID 41194247, 2025). "In summary, GZMB serves as a crucial effector molecule in tumor immunity and holds considerable therapeutic promise." (PMID 41567188, 2025). "Plasmacytoid dendritic cells can also produce GZMB independently of perforin, leading to suppression of T-cell activation and contributing to tumor growth." (PMID 40766321, 2025). "This was due to the fact that combined blockade resulted in higher levels of cytokines (IFN-γ, TNF-α, and granzyme B) production by tumor-specific CD8+ T cells from tumor-draining lymph nodes compared to single blockade or control group 142." (PMID 40861801, 2025). "Increased levels of IFN‐γ, perforin, and granzyme B indicate heightened CTL cytotoxicity directed against the tumor." (PMID 40498983, 2025). "Granzyme B is often indicated as a potential ideal biomarker for immune response, especially applications in monitoring of tumor immunotherapy." (PMID 40766321, 2025). "Although the absolute number of CD8+ T cells in combination treated tumours is lower than the PI3Kγ monotherapy group, they are more cytotoxic with elevated expression of granzyme B, perforin and TIGIT, indicating a checkpoint-engaged phenotype." (PMID 39788719, 2025). "Blood CD8 T cells in mice with advanced liver fibrosis exhibit IFN‐γ and granzyme B hyperfunction, and animal responses to ectopic tumour challenge and immunotherapy are impaired." (PMID 40760842, 2025). "In contrast, YD treatment resulted in significant CD8+ T cell infiltration throughout the tumor core, increased granzyme B expression, and a moderate elevation in PD‐1 levels." (PMID 40108893, 2025).
tumor (continued). "Given that CD8+ CTLs eliminate cancer cells by secreting granzyme B (GB), a potent inducer of tumor cell apoptosis, we investigated the CD8+ CTL population and CTL activity by measuring GB release." (PMID 39961271, 2025). "The HDAC inhibitor Vorinostat doubles CD8+ T-cell granzyme B expression, elevating tumor killing efficiency by 80%." (PMID 41415289, 2025). "Compared to SLAMF7− DNT, adoptively transferred SLAMF7+ DNT had an increased tumor-infiltrating level, elevated Ki67 expression, and significantly elevated production of cytotoxic molecules, such as granzyme A, granzyme B and perforin." (PMID 41168829, 2025). "These engineered T cells can also induce tumor cell death through granzyme B (GzmB) and Fas ligand (FasL) pathways." (PMID 40006624, 2025). "In the interface region, the profile of immune response markers differed from that of the tumor core by exhibiting two major groups of immune responses that diverged in terms of Granzyme B+ cell infiltration." (PMID 40469283, 2025). "Analysis of IHC staining showed that the expression levels of CD8, IFN-γ, and GZMB were significantly upregulated in tumor tissues with CTSE knockdown and the anti-PD-1 combination treatment group." (PMID 40467555, 2025). "Other cytokines relevant to tumor clearance, such as Granzyme B and IL‐17, were also regulated in a patient‐specific manner, with increased secretion of both mediators observed in six out of eight and four out of eight donors, respectively." (PMID 40952312, 2025). "Receiving a timely response to immunotherapy and monitoring the activity of granzyme B in tumor cells are crucial aspects." (PMID 40585764, 2025). "CD8+ cytotoxic T lymphocytes are essential for recognizing and eliminating tumor cells through direct cytolytic activity and the release of pro-apoptotic mediators such as perforin and granzyme B." (PMID 41426320, 2025). "GZMB, as the primary effector molecule in CTLs and NK cells, has been traditionally recognized for its anti-tumor properties through the induction of target cell apoptosis." (PMID 41567188, 2025). "We examined the expression of granzyme B (GZMB)—a key effector molecule of activated cytotoxic T cells for tumor killing." (PMID 40585994, 2025). "CD8+ T cell exhaustion, identified by co-expression of inhibitory receptors like PD-1, TIM-3, LAG-3, TIGIT, and decreased cytotoxic markers like granzyme B and perforin, was observed in both tumor-infiltrating lymphocytes (TILs) and peripheral blood." (PMID 41375063, 2025). "First, we used the WTA protocol to evaluate the infiltration of Tregs, CCR8+ Tregs, CD8+ T cells, and GzmB+ CD8+ T cells to the whole tumor area." (PMID 41323783, 2025). "Upon recognition of a target cell by these immune cells, GZMB is delivered into the target cell via pores created by perforin in the cell membrane, where it exerts its anti-tumor effects through the cleavage of specific substrates." (PMID 41567188, 2025). "Meanwhile, the percentage of IFN‐γ+GzmB+CD8+ T cells within tumor tissues was increased, whereas that of PD‐1+Tim‐3+CD8+ T cells was decreased in the CX4945 group and the CX4945 plus anti‐PD‐1 therapy group compared to the control group." (PMID 40013761, 2025). "Here, we demonstrate that CD4+ but not CD8+ anti-TGF-β CAR T cells (T28zT2 T cells) can suppress tumor growth partly through secreting Granzyme B and interferon (IFN)-γ." (PMID 40107245, 2025). "Sting knockdown reduced CD8+ T cells, granzyme B+, IFN‐γ+, and NK cells, and increased MDSCs in tumor tissues, and reversed the immunophenotype caused by Rfwd3 knockdown, suggesting the role of STING inhibition in RFWD3‐caused pro‐tumor TME." (PMID 41117130, 2025). "Vδ2+ cells generally contribute to antitumor immunity by secreting IFN-γ and TNF-α and inducing tumor cell lysis through secreting perforin, granzyme B, and TRAIL." (PMID 40746558, 2025). "In various cancers, increased GZMB expression correlates significantly with tumor invasion, metastasis, and poor prognosis." (PMID 41567188, 2025).
tumor (continued). "Exosomes from activated NK cells (primary or NK92), stimulated with IL-2, IL-12, and IL-15, display increased penetrability, solid tumor targeting capacity, and enhanced cytotoxicity against tumor cells, attributed to granzyme B and H enrichment." (PMID 41511353, 2025). "This innovation facilitates precise tumor antigen targeting, robust costimulatory signaling, and the production of effector molecules, such as interferon-γ, granzyme B, and perforin, that effectively eradicate tumor cells." (PMID 40093905, 2025). "Targeting DCA-producing Clostridium scindens by bacteriophages significantly reduces the expression of TNF-α, IFN-γ and granzyme B in intratumoral T cells, subsequently abolishing tumor growth in CRC." (PMID 40770084, 2025). "ELISA analysis demonstrated significantly increased secretion of Perforin-1 and Granzyme-B in KO-HMGB2 NK cells in response to tumor stimulation." (PMID 41280896, 2025). "In agreement, the expression levels of CD8+ T cell‐derived cytotoxic mediators, such as IFN‐γ, granzyme B, and perforin, showed a robust increase only in the tumor tissues of αPD‐L1‐treated CFD mice." (PMID 40637137, 2025). "Activated iNKT cells can directly kill CD1d+ tumor cells by releasing perforin and granzyme B, as well as through Fas/FasL interactions." (PMID 40698085, 2025). "Recent studies have identified cytotoxic CD4+ T cells (activated TH1 cells) that directly kill tumor cells by releasing granzyme B and perforin." (PMID 40176817, 2025). "The expression of T cell activation receptor IL2R, along with various anti-tumor secretory factors (GZMB, IFNγ) and the inflammatory cytokine IL2, showed strong correlation with intracellular NAD+ levels." (PMID 40846839, 2025). "CAR-NK cells are cytotoxic innate lymphoid cells that eliminate tumor cells through the release of granzyme B, perforin, TRAIL, and Fas ligand." (PMID 40723278, 2025). "Our in vitro studies revealed that uPA–/– CD8+ T cells exhibited enhanced tumor-killing activity through the secretion of GzmB, IFN-γ, and TNF-α." (PMID 40959092, 2025). "For example, butyrate-producing R. intestinalis suppresses tumor growth by expanding cytotoxic granzyme B+, IFN-γ+ and TNF-α+ CD8+ T cells, concurrently enhancing anti-PD-1 efficacy in mice with MSS CRC." (PMID 40770084, 2025). "The probes demonstrated high specificity toward GzmB, allowing for real-time imaging and optical urinalysis of the immunoactivities at the tumor sites." (PMID 41375132, 2025). "In tumor-bearing mice, lung tumors grew significantly slower, and the amount of granzyme B+CD8+T cells was greater in fibroblast-specific CD248 gene knockout mice than in wild-type mice." (PMID 40735646, 2025). "Once inside, granzyme B activates caspase-dependent apoptotic pathways, leading to tumor cell death." (PMID 40226616, 2025). "Targeting granzyme B, which is overexpressed in tumours or inflammatory regions, is promising for imaging the atherosclerotic diseases, systemic lupus erythematosus." (PMID 39747850, 2025). "Conversely, SURF4 overexpression in T cells significantly reduced the expression of activation markers (CD3D, CD69) and anti-tumor proteins (GZMB), while simultaneously suppressing the p-STING/p-IRF3 axis." (PMID 40846839, 2025). "GZMB + cells can release GZMB, which primarily participate in cytotoxic immune responses and can induce apoptosis of tumor cells." (PMID 40264767, 2025). "These reprogrammed TANs formed immune cell clusters in direct contact with CD8+ T cells, which were enriched with anti-tumor granzyme B, indicating a synergistic interaction between TANs and CD8+ T cells, enhancing the anti-tumor effect." (PMID 40573881, 2025). "Instead, it was seen that these MVs had FasL, granzyme A, granzyme B, and perforin in their composition, suggesting their role in the anti-tumor apoptotic process." (PMID 40149564, 2025). "Flow cytometry and mIHC corroborated the enhanced production of IFN-γ and GZMB in tumor-infiltrating CD8+ T cells from ENO1-KO samples." (PMID 40665335, 2025).
tumor (continued). "Both exosomes derived from NK92 cells and CAR-NK92 cells express granzyme B, suggestive for a potential cytotoxic effect against tumor cells." (PMID 40806778, 2025). "Both, ILs and free P60 (at a dose 50 times higher than encapsulated) were able to increase statistically IFNγ levels and Granzyme B expression in tumor CD8+ T cells." (PMID 39075226, 2025). "Both the Niraparib and Ezetimibe monotherapy groups promoted the infiltration of CD8+ T cells and increased the secretion of Granzyme B in the tumor tissue." (PMID 40430847, 2025). "Among these, CD8+ T cells are pivotal for tumor control due to their capacity to recognize cancer-specific antigens and exert cytotoxic effects through the release of perforin and granzyme B." (PMID 40699668, 2025). "IHC analysis of spheroids collected during the assay revealed effective T-cell infiltration into the 3D tumor structure (CD3), signs of T-cell activation (granzyme B, PD-1), and apoptotic tumor cells (cleaved caspase 3) while sparing CAFs (vimentin)." (PMID 39404622, 2025). "Human pDCs, a specialized subset of dendritic cells that bridge innate and adaptive immunity, also significantly contribute to tumor-promoting GZMB activities." (PMID 41567188, 2025). "CD8+ T cells, key effectors of anti-tumor immunity, can induce apoptosis in cancer cells through the release of cytotoxic molecules like perforin and granzyme B." (PMID 40281780, 2025). "Tumor-associated macrophages induced apoptosis of CD8+ T cells and impair cytotoxic functions by reducing granzyme B and perforin expression in the liver." (PMID 40651961, 2025). "We observed an increased trend in the quantity of GZMB+LA within remnant tumor nodules in LNP-CTNNB1 + α-PD1 compared to LNP-CTNNB1 + IgG treated mice (p = 0.0989)." (PMID 40442146, 2025). "Similar patterns of perforin expression were seen also for cytotoxic CD8+ T cells in untreated patients, except their GZMB-only expressing cells were less regulated by KLRG1 in tumor." (PMID 40299576, 2025). "Multicolor immunofluorescence analyses of AITL samples revealed that SLC3A2 expression in tumor cells was inversely correlated with granzyme B+CD8+ T‐cell infiltration." (PMID 40344476, 2025). "In vivo, PTE suppressed tumor growth and remodeled the tumor microenvironment by increasing granzyme B+, TNF-α+, and IFN-γ+ CD8+ T cells while reducing myeloid-derived suppressor cells and regulatory T cells." (PMID 41181138, 2025). "The body weight remained consistent across all groups.Flow cytometry analysis revealed that NAT10 knockdown significantly increased CD8 + T cell infiltration and granzyme B levels, indicating enhanced anti-tumor immunity." (PMID 41203621, 2025). "Flow cytometry and mIF analyses revealed a significant increase in the proportion of granzyme B+ CD8 T cells in the tumour microenvironment of mice treated with anti‐PD‐1 in the PDL2 EVs injection group." (PMID 40135876, 2025). "Above-median expression of GZMB and PRF1 in tumor at progression was also associated with longer median OS (42 months vs. 13 months and 42 months vs. 11 months, respectively)." (PMID 40239619, 2025). "Genes associated with increased cytotoxicity (GZMB, GNLY, PRF1), and anti-tumor activity (NKG7) were upregulated in the cytotoxic lymphocytes, including CD8 + T cells, γδ T cells, NK cells, and ILCs." (PMID 41194247, 2025). "These cytotoxic CD4+ T cells express granzyme K and granzyme B and exhibit the ability to kill autologous tumor cells in an MHC-II-dependent fashion, suggesting a direct role in tumor destruction." (PMID 40177538, 2025). "By secreting cytotoxic molecules such as perforin and granzyme B, they precisely punch holes in the tumor cell membranes, inducing apoptosis." (PMID 41415289, 2025). "Further examination revealed that Tocilizumab treatment markedly upregulated NKp30 expression on NK92 cells within the tumor microenvironment and enhanced their granzyme B secretion capacity." (PMID 41254082, 2025).
tumor (continued). "These cytokines, including CCL5 and CXCL10, up‐regulate tumour cell lysis via large amounts of granzyme B.40, 41Collectively, the activation of the classical pathway results in immunosuppression against tumours." (PMID 41275427, 2025). "Roseburia intestinalis inhibits tumor growth by inducing cytotoxic granzyme B+, IFN‐γ, and TNF‐α + CD8 + T cells, significantly enhancing the anti‐PD‐1 efficacy in mice carrying MSI low CT26 tumors." (PMID 40530896, 2025). "This review further aims to explore and compare the distinct, yet potentially complementary roles of granzyme B and melittin in tumor cell elimination and their translational potential in cancer immunotherapy." (PMID 40766321, 2025). "Sequential biopsies demonstrated increased CD8+ T and CD4+FOXP3− T-cell infiltration and granzyme B (GZMB) overexpression, indicating tumour immunity activation by visugromab." (PMID 41294666, 2025). "Some regulatory B cells subtypes produce GZMB and can inhibit T-cell proliferation by degrading key molecules in T-cell receptors, thereby reducing anti-tumor immune responses." (PMID 40766321, 2025). "NKT cells exhibit direct cytotoxicity against tumor cells via the Fas/FasL pathway, leading to the release of perforin, granzyme B, and TNF-α." (PMID 40070843, 2025). "We found several key anti-tumor Th1 cytokines such as interleukin (IL)-2, IL-4, and interferon-γ, were stimulated by the combination therapy either systemically or in tumors or both, as well as anti-tumor biomarkers such as Granzyme B and perforin." (PMID 40104170, 2025). "Cytotoxic lymphocytes, including T cells and natural killer (NK) cells, are key mediators of tumor suppression, acting through the release of signaling molecules such as perforin and granzyme B (GrB)." (PMID 40347254, 2025). "CD8+ T cells that exhibited high expression levels of exhaustion gene (HAVCR2, ENTPD1, LAG3, PDCD1, CXCL13, TOX, and GZMB) in the primary tumor were extracted and clustered." (PMID 40364834, 2025). "Upon reinfusion, CAR-T cells recognize tumor surface antigens via their scFv domains, form immunological synapses, and release perforin and granzyme B to mediate direct cytotoxicity." (PMID 40904467, 2025). "IHC staining of tumour tissues for GzmB revealed that the number of GzmB+ cells exhibited a consistent trend with the CD8+ T cell counts quantified using flow cytometry." (PMID 40715695, 2025). "Elevated levels of GZMB in tumor infiltrating lymphocytes (TIL) correlate with better clinical outcomes in patients under-going therapy with immune checkpoint inhibitors." (PMID 40766321, 2025). "We also found that caspase 3/7 activity correlated with elevated GZMB levels in tumor cells, supporting enhanced T cell-mediated killing." (PMID 41444249, 2025). "In this in vivo model, CTSS knockdown resulted in increased infiltration of CD8+ T-cells expressing granzyme B along with enhanced autophagy markers and reduced PD-L1 expression in tumor cells." (PMID 40794185, 2025). "Direct killing of tumor cells: Upon activation, γδ T cells can directly induce tumor cell lysis by liberating perforin and granzyme B." (PMID 40558272, 2025). "Several studies have reported that THBS1 interaction with CD47 on NK cells and cytotoxic T cells inhibits their activation and limits granzyme B production that mediates antigen-dependent lysis of tumor cells." (PMID 41019041, 2025). "ROS also enhance the cytolytic activity of NK cells by promoting the release of perforin and granzyme B, and promote the recruitment and activation of anti-tumor N1 type neutrophils, further exerting anti-tumor effect." (PMID 40424719, 2025). "Conversely, the depletion of NUAK1 notably increased both the quantity and activity (GZMB+) of CD8+ T cells in the tumor." (PMID 39901136, 2025). "By a coculture system, we found that CD8+ T cells with PAN3-AS1 or WFDC13 knockdown tumor cells exhibited higher granzyme B production and enhanced Ki67 activity." (PMID 41502505, 2025).